SMAD2 (SMAD family member 2)
Diseases named in the same sentence as SMAD2 in open-access papers (continued):
Sharing a sentence is not in itself a finding about the gene and the disease.
head and neck squamous cell carcinoma (4 papers, 2010 to 2025). A squamous cell carcinoma that arises from any of the following anatomic sites: lip and oral cavity, nasal cavity, paranasal sinuses, pharynx, larynx, and salivary glands. "In accordance, the Smad expression profile assessed by tissue array in 170 head and neck squamous cell carcinoma pointed to the loss of TGFβ/Smad2 signaling as a possible cause of adverse outcome." (PMID 20462450, 2010). "Further, SMAD2 and SMAD4 as the two essential components of the TGF beta-Smad signaling pathway also have such variant pattern contributing to the tumorigenesis of head and neck squamous cell carcinoma in contrast with other tumor types." (PMID 34513841, 2021).
Infertility (4 papers, 2020 to 2025). "In UI infertility, alterations in SMAD2 and SMAD2/3 signaling could potentially impact reproductive functions." (PMID 40428359, 2025).
lymph node metastasis (4 papers, 2010 to 2025). "In CAFs, high periostin expression was significantly correlated with high Smad2/3 expression, increased invasion depth, lymph node metastasis, venous invasion, advanced disease stage, and a higher rate of relapse." (PMID 39941916, 2025). "In the high lymph-node metastasis (N2 and N3) group, SMAD2 expression was more frequent, as was ERBB2 and MET expression." (PMID 35650563, 2022). "Upregulation of Smad2 and Smad4 proteins were also significantly correlated with lymph node metastasis, distant metastasis, advanced stage, and poor survival (p < 0.0001)." (PMID 35456495, 2022). "In the present study, p-Smad2 expression in tumour cells was significantly higher in diffuse-type tumours and in cases with peritoneal metastasis, free peritoneal cancer cells and lymph node metastasis." (PMID 21110833, 2010).
malignant glioma (4 papers, 2015 to 2025). A grade III or grade IV glioma arising from the central nervous system. "In conclusion, the present study provided evidence that the Smad3 pathway is important in malignant glioma cells and suggested that Smad2 and Smad3 have tumor suppressor activities." (PMID 25891822, 2015). "TGF-β1 induced autophagy and activated AEG-1 via Smad2/3 phosphorylation in malignant glioma cells." (PMID 26909607, 2016). "Considering these results, the preset study hypothesized that the ability to resist TGFβ2-mediated growth inhibition in malignant glioma cells was due to a decrease in the expression levels of Smad2 and Smad3 in the TGFβ2 signaling pathway." (PMID 25891822, 2015). "A recent study reported that in TGF-β treated malignant glioma, MTDH protein was increased via Smad2/3 phosphorylation." (PMID 30065618, 2018).
papillary thyroid cancer (4 papers, 2021 to 2025). "Crucially, our experiments revealed that knockdown of TAGLN2 in thyroid papillary carcinoma cells led to a significant decrease in p-Smad2 levels, indicating an attenuation of TGF-β signaling activation." (PMID 41169389, 2025). "Moreover, curcumin was demonstrated to inhibit metastasis in human papillary thyroid carcinoma cells by downregulating components of the prometastatic signaling pathway TGFB1/SMAD2/SMAD3." (PMID 34422220, 2021). "Although some studies in other cancers indicated that SIX1 regulates EMT processes through the TGF-β/Smad2/3 signaling pathway in papillary thyroid cancer, there is no direct evidence that SIX1 induces EMT via the TGF-β/Smad2/3 signaling pathway in GC." (PMID 35458126, 2022).
retinoblastoma (4 papers, 2019 to 2022). A malignant tumor that originates in the nuclear layer of the retina. "We previously found that the ACVR1C/SMAD2 pathway is significantly upregulated in invasive retinoblastoma samples from patients." (PMID 31451106, 2019). "Previously, SMAD2 has been reported to be highly expressed in retinoblastoma and its overexpression facilitated the proliferating and metastatic processes of RB cells." (PMID 34969359, 2021). "The inhibition of ACVR1C/SMAD2 pathway using a selective inhibitor of ALK4/5/7 receptors, or down-regulation of ACVR1C or SMAD2 by shRNAs, suppressed retinoblastoma cells lines derived from primary tumors or vitreous." (PMID 35954181, 2022). "In agreement with a previous report stating that retinoblastoma cells lack functional TGFβ receptors I and II, we identified that ACVRC1 receptors, which is a member of the TGFβ family, could accelerate SMAD2 activations in advanced retinoblastoma." (PMID 36291907, 2022).
systemic sclerosis (4 papers, 2015 to 2023). A chronic disorder, possibly autoimmune, marked by excessive production of collagen which results in hardening and thickening of body tissues. "Curcumin disturbs the TGF-β signaling in systemic scleroderma (SSc), by counteracted phosphorylation of Smad2 and induced upregulation of TGF-β-induced factor (TGIF)—a negative regulator of TGF-β signaling." (PMID 25708189, 2015). "Administration of Astragalus polysaccharide in bleomycin-induced systemic sclerosis mice reduced the collagen production in skin tissue, also downregulating the TGF-β1, MCP-1, Smad2, and Smad3 mRNA expressions." (PMID 34258301, 2021).
Aortic dissection (3 papers, 2023 to 2024). Aortic dissection refers to a tear in the intimal layer of the aorta causing a separation between the intima and the medial layers of the aorta. "It is also consistent with our earlier findings that Smad2 phosphorylation levels in the aorta of Fbn1mgR/mgR mice increase at a later stage than P45, and that systemic TGF-β neutralization between P16 and P45 dramatically accelerates the incidence of acute aortic dissection and rupture." (PMID 37022786, 2023).
aristolochic acid nephropathy (3 papers, 2011 to 2021). "This may explain CD8+ T-cell tubulitis and associated TGF-β1/Smad2/3 signaling activation in a rat model of aristolochic acid nephropathy (AAN)." (PMID 33718407, 2021). "Smad2 has also been demonstrated to mediate renal interstitial fibrosis development in mice with experimental aristolochic acid nephropathy." (PMID 22174924, 2011).
Arthritis (3 papers, 2017 to 2023). Inflammation of a joint. "A previous study shows that SMAD2 is vital in arthritis and the proliferation and migration of chondrocytes can be inhibited upon SMAD2 knockdown." (PMID 35090521, 2022).
cardiomyopathy (3 papers, 2019 to 2023). A disease of the heart muscle or myocardium proper. "Here we showed a two- fold increase in circulating TGF-β levels, which is consistent with an increase in phosphorylated Smad-2/3 in the heart tissue, corroborating data found in the cardiac tissue of CD patients with cardiomyopathy." (PMID 31365537, 2019). "In silico analysis showed several of these piRNAs were computationally predicted to target and potentially regulate expression of genes including SMAD2, EGR1, ICAM1, CX3CL1, and CXCR2, which have been implicated in parasite infection, pathogenesis, and various cardiomyopathies." (PMID 36936778, 2023).
cholangiocarcinoma (3 papers, 2020 to 2024). A carcinoma that arises from the intrahepatic biliary tree (intrahepatic cholangiocarcinoma) or from the junction, or adjacent to the junction, of the right and left hepatic ducts (hilar cholangiocarcinoma). "In high circ_0020256 expression cholangiocarcinoma, cancer cell-secreted transforming growth factor β1 (TGF)-β1 promotes CAFs activation via Smad2/3 phosphorylation." (PMID 39759028, 2024). "circ_0020256 is highly expressed in cholangiocarcinoma (CCA) and enhances CCA cells’ secretion of TGF-β1, which subsequently activates CAFs via Smad2/3 phosphorylation." (PMID 39534084, 2024).
chondrosarcoma (3 papers, 2012 to 2017). A malignant cartilaginous matrix-producing mesenchymal neoplasm arising from the bone and soft tissue. "Induction of Peg10 mildly but significantly inhibited the activity of TGF-β-SMAD2/3-responsive 9xCAGA luc in not only C28/I2 chondrocytes but also chondrosarcoma cell lines." (PMID 29044189, 2017). "They found strong activation of both SMAD1/5/9 and SMAD2 in chondrosarcomas in a grade-dependent fashion, while a high rate of phosphorylated SMAD2 was associated with shorter metastasis-free survival." (PMID 29044189, 2017). "Herein, we determined the effects of FYD on the expression of transcription factor SOX9 and its target gene collagen type II, alpha 1 (COL2A1) as well as the activation of Smad2/3 in interleukin- (IL-) 1β-stimulated SW1353 chondrosarcoma cells." (PMID 26770254, 2015). "Nuclear phosphorylated Smad1/5/8 and Smad2 were found in all tumors analyzed and the activity of both signaling pathways was confirmed by functional reporter assays in 2 chondrosarcoma cell lines." (PMID 23088614, 2012). "In order to establish whether the BMP and TGFβ signaling pathways are active in central chondrosarcoma, the presence of nuclear phosphorylated Smad1/5/8 and Smad2 was evaluated by immunohistochemical analysis." (PMID 23088614, 2012). "Phosphorylated Smad1/5/8 and Smad2 was detected in all chondrosarcoma samples analyzed." (PMID 23088614, 2012). "Our reporter assay indicates that the Smad1 and Smad2 signaling pathways may not be relevant for proliferation of chondrosarcoma cells." (PMID 23088614, 2012).
congenital heart disease (3 papers, 2014 to 2024). "An interesting example from the CMG dataset is for a de novo variant in SMAD2, which is associated with an autosomal dominant form of congenital heart disease." (PMID 28977528, 2017). "The role of Smad2 has been reported in diseases such as congenital heart defects and growth restriction." (PMID 39201474, 2024). "Having defined parameters that permit efficient Cas9-mediated gene knockout in mESCs, we next targeted Smad2, MLL2, and CHD7, mutations of which have been implicated in human congenital heart disease." (PMID 25166277, 2014).
Crohn disease (3 papers, 2018 to 2022). A gastrointestinal disorder characterized by chronic inflammation involving all layers of the intestinal wall, noncaseating granulomas affecting the intestinal wall and regional lymph nodes, and transmural fibrosis. "Upregulation of endogenous IGFBP3 and TGF-β1 expression enhances excess collagen IαI production in SMCs and contributes to fibrosis and stricture formation in Crohn's disease via a TGF-βRII/I-dependent and Smad2/3-dependent mechanism." (PMID 35154570, 2022).
cyst (3 papers, 2011 to 2020). A sac-like closed membranous structure that may be empty or contain fluid or amorphous material. "Here we confirmed Smad2 was activated (phosphorylated) by TGF-β1 in a time-dependent manner and the up-regulation of P-Smad2 was reduced in rosiglitazone-treated ADPKD cyst lining epithelial cells." (PMID 22174924, 2011). "Since activation of Smad2 was the major downstream event of TGF-β1 signaling, we first investigated the phosphorylation of Smad2 in human ADPKD cyst-lining epithelial cells." (PMID 22174924, 2011). "ADPKD cyst-lining epithelial cells pretreated with PD98059 or SB203580 did not influence the activation of Smad2 on TGF-β1 treatment." (PMID 22174924, 2011). "Paradoxically, genetic disruption of the ALK5 receptor in renal epithelial cells did not affect cyst formation/growth and only slightly reduced expression of SMAD2/3 target genes, while the activin ligand trap, sActRIIB-Fc, significantly slowed down PKD progression in mice." (PMID 28168444, 2017).
esophageal cancer (3 papers, 2021 to 2022). A primary or metastatic malignant neoplasm involving the esophagus. "This, in turn, contributed to secretion of high levels of TGF-β1 by M2 macrophages and promoted esophageal cancer cell epithelial-mesenchymal transition via the TGF-β/Smad2 axis." (PMID 34439276, 2021). "This may result in esophageal cancer cell epithelial-mesenchymal transition (EMT) via TGF-β/Smad2 signaling." (PMID 34439276, 2021).
gastric adenocarcinoma (3 papers, 2010 to 2015). "In the present study, we investigated the potential role of differential Smad2/3 phosphorylation in gastric adenocarcinoma." (PMID 22539990, 2012). "We also evaluated the relationship between the expression levels of p-Smad2 and clinicopathologic characteristics of patients with gastric adenocarcinomas." (PMID 21110833, 2010). "Immunohistochemical staining with anti-p-Smad2 was performed on paraffin-embedded specimens from 135 patients with advanced gastric adenocarcinomas." (PMID 21110833, 2010). "The aim of the current study is to clarify the role of phosphorylated Smad2 (p-Smad2) in gastric adenocarcinomas at advanced stages." (PMID 21110833, 2010).
Hepatic steatosis (3 papers, 2021 to 2024). Steatosis is a term used to denote lipid accumulation within hepatocytes. "Taken together, our findings reveal that exosomes derived from rats with OSA increase the risk of hepatic steatosis in MASLD by regulating the expression of TCONS_00039830/miR-455-3p/Smad2 in hepatocytes." (PMID 38654054, 2024). "Overall, these results indicated the significance of the TCONS-00039830/miR-455-3p/Smad2 axis in FFA-induced liver steatosis." (PMID 38654054, 2024). "Intracellular fat accumulation was evaluated in the FFA + si-TCONS-00039830, FFA + miR-455-3p mimic and FFA + TCONS-00039830 + miR-455-3p mimic groups to examine the role of TCONS-00039830/miR-455-3p/Smad2 in hepatic steatosis." (PMID 38654054, 2024). "Our results revealed that exosomes derived from rats with OSA promoted hepatic steatosis to increase the severity of liver damage in MASLD, and the possible molecular mechanism is the increased activity of the TCONS_00039830/miR-455-3p/Smad2 axis." (PMID 38654054, 2024).
Hypercholesterolemia (3 papers, 2022 to 2023). An increased concentration of cholesterol in the blood. "A significant decrease in these cell signaling markers were observed following BMP-7 treatment, suggesting the efficacy of BMP-7 in attenuating hypercholesterolemia-induced TGF-β1, Smad2, and Smad3 proteins." (PMID 36829889, 2023). "Our data showed that, in diabetic mice, gene expressions of TGF-β1, Smad2, and Smad3 were significantly (p < 0.05) increased as compared with the control mice, suggesting a role of the TGF-β/Smad cell signaling pathway in hypercholesterolemia-induced pyroptosis and diabetic progression." (PMID 36829889, 2023). "In a hypercholesterolemia-driven mouse model of CAVD, cholesterol-lowering strategies reduced calcification but not fibrosis or Smad2 signaling, and this effect was attributed to the selective down-regulation of Smad6." (PMID 36139812, 2022).
hyperlipidemia (3 papers, 2017 to 2026). "Restoring TGF-β/Smad2 signaling represents a promising therapeutic strategy to mitigate hyperlipidemia-induced tendon damage and poor healing." (PMID 42078444, 2026).
infarction (3 papers, 2017 to 2024). A localised pathological necrosis of tissue resulting from obstruction of the blood supply usually by a thrombus, an embolus, or vascular torsion. "As both processes are mediated via TGFβ/SMAD2 signaling, interference with this pathway should be a major aim for prevention of myocardial damage due to infarction." (PMID 29088068, 2017).
interstitial lung disease (3 papers, 2020 to 2022). A diverse group of lung diseases that affect the lung parenchyma. "A recent study has reported that miR-7 regulated Smad2 activation and significantly participated in interstitial lung diseases." (PMID 35700140, 2022).
intrahepatic cholangiocarcinoma (3 papers, 2016 to 2022). A carcinoma that arises from the intrahepatic bile duct epithelium in any site of the intrahepatic biliary tree. "Silencing of S100A11 in intrahepatic cholangiocarcinoma can reduce the level of SMAD2/3 phosphorylation which is induced by TGF-β1, and then inhibit cell migration, invasion and epithelial-mesenchymal transition (EMT)." (PMID 35752610, 2022). "Study has shown that S100A11 promotes epithelial mesenchymal transformation of intrahepatic cholangiocarcinoma induced by TGF-β1 through the Smad2/3 signaling pathway." (PMID 34663163, 2021).
lupus (3 papers, 2016 to 2025). "We further cultured the HK2 cells with TGF-β1; the studies revealed significant phosphorylation of p38 MAPK and Smad2 proteins as in lupus mice." (PMID 27365897, 2016). "In the NZB/WF1 mouse model of systemic lupus erythematosus (SLE), mice in the low-LF diet group were able to significantly increase antioxidant activity and inhibit hepatic fibrosis by decreasing the expression of fibrotic cytokines and Smad2/3 activation." (PMID 39796631, 2025). "In conclusion, TWEAK may contribute to the pathogenesis of kidney remodeling through activating TGF-β signaling by inducing the phosphorylation of Smad2 and p38 MAPK proteins in lupus mice." (PMID 27365897, 2016). "SMAD2, GATA3, and FOXO3 could also be the miR-200a-3p targets in SLE and our lupus-like models." (PMID 29349090, 2017).
metastatic cancer (3 papers, 2017 to 2020). A carcinoma which has spread from the original site of growth to another anatomic site. "Linker phosphorylation of Smad2 and Smad3 may represent a target for intervention in human metastatic cancer." (PMID 28471448, 2017). "Interestingly, it was described that the non-canonical TGFβ pathway is inappropriately activated in metastatic cancer cells and interferes with the SMAD2/3-mediated tumor suppressing message." (PMID 32429474, 2020).
metastatic tumours (3 papers, 2015 to 2017). "Protein lysates from SB-431542 treated MFE-296 tumours showed an expected decrease in Smad phosphorylation, whereas higher p-Smad2 expression was observed in MFE-296 primary tumours (1.9-fold) and metastatic tumours (2.6-fold) compared to Ishikawa tumours at the primary site." (PMID 29069715, 2017). "Further experiments on RCC cell lines - Caki-2 (primary tumor) and SK-RC-52 (metastatic tumor) – have shown that IGF-I enhances transforming growth factor (TGF)-beta signaling including phosphorylation and nuclear translocation of mothers against decapentaplegic homolog 2 (Smad2)." (PMID 27405474, 2016).
nasal polyps (3 papers, 2017 to 2023). "Compared with IT, the mRNA expression and protein level of TGF-β1/PAI-1/t-PA/Collagen1 was lower in eNP group, while Smad2 presented no statistical significance, which is in line with predilection site of nasal polyps in uncinate tissue in the middle meatus." (PMID 36841712, 2023). "Taken together, our results suggest that 1,25(OH)2D3 might be an effective therapy for nasal polyps by reducing myofibroblast differentiation and ECM production mediated by Smad2/3-dependent TGF-β1 signaling pathways in NPDFs." (PMID 28779150, 2017). "TGF-βR3 and phosphorylated SMAD2 levels were downregulated in CRSwNP compared with controls and CRS without nasal polyps with a more prominent downregulation in the eosinophilic CRSwNP." (PMID 36976645, 2023).
postmenopausal osteoporosis (3 papers, 2019 to 2020). Metabolic disorder associated with fractures of the femoral neck, vertebrae, and distal forearm. "Similarly, miR-214-5p overexpression diminished levels of ALP, Runx2, OCN and COLI, and TGFβ/Smad2 in bone marrow stem cells of postmenopausal osteoporosis." (PMID 33935961, 2020). "The TGF‐β1 and Smad‐2/3 signaling pathway could be a therapeutic target of TGP in postmenopausal osteoporosis rats." (PMID 30834706, 2019). "It is worth mentioning that regulation of the TGF‐β/Smad2/COL4A1 signaling pathway promotes osteogenic differentiation of bone marrow stromal cells and is of great significance for the new treatments strategy for postmenopausal osteoporosis." (PMID 32496000, 2020).
renal cell carcinoma (3 papers, 2023 to 2024). "In addition, in renal cell carcinoma cells in vitro, overexpression of HMGA2 facilitated the EMT process through the TGFβ/SMAD2 signaling pathway." (PMID 38361784, 2024).